ICAM1 (intercellular adhesion molecule 1)
Diseases named in the same sentence as ICAM1 in open-access papers (continued):
Sharing a sentence is not in itself a finding about the gene and the disease.
tumor (continued). "Accumulating data indicate that IL-1β activates 2 major downstream effectors, the NF-κB and MAPK pathways, to stimulate the expression of adhesion molecules such as ICAM1 and VCAM1 in diverse cell types including tumor cells, thereby amplifying and sustaining responses to IL-1β." (PMID 36264639, 2022). "Overexpression of ICAM-1 in tumor cells significantly improves T-cell cytotoxicity and effector function, thus leading to tumor regression without apparent negative side effects on T cells." (PMID 35681548, 2022). "ICAM-1 increased lymphocytes recruitment, promoted lymphocytes to attach to CRC cells and lymphocyte-mediated tumor lysis, which may improve the immunosurveillance and restrict tumor metastasis." (PMID 36505809, 2022). "Nevertheless, The elimination of the primary E0771 tumor by Treg depletion was not reduced when ICAM-1 was deleted on target E0771 cells." (PMID 35911772, 2022). "In addition, VEGF 44, ICAM-1 45-47, TGF-β 48, IL-2, IL-649-51, and TNF-α 52 play an important role in the growth and metastasis of tumor cells, and can affect the expression of co-inhibitory molecules on immune cells." (PMID 36118529, 2022). "The cell-cell adhesion signaling pathway is responsible for tumor invasion and metastasis by regulating a series of genes including matrix metallopeptidase (MMP), integrin subunit alpha (ITGA), and immunoglobulin-like cell adhesion molecule 1 (ICAM1)." (PMID 36482371, 2022). "For instance, tumor cells that are entrapped within NETs from neutrophils act as passengers, whereby neutrophils that express CD11a (LFA1) and CD11b (Mac-1) are able to interact with ICAM-1 on endothelial cells." (PMID 35207611, 2022). "Such conditions, combined with the induction of expression of adhesion molecules such as vascular cell adhesion molecule 1 (VCAM-1) and intercellular adhesion molecule 1 (ICAM-1) (also mediated by TGF-β), are conducive to immune cell infiltration into the tumor microenvironment." (PMID 36499660, 2022). "In addition, ATO simultaneously attenuated the expression of ICAM1 and its related CSC marker, CD44, in tumor tissues on costaining analysis." (PMID 36264639, 2022). "There are some reports that have attributed a pro-metastatic role for the interaction of neutrophil CD11b/CD18 (Mac-1) with ICAM-1 on selected tumor cells, and the interaction of neutrophil L-Selectin with mucin and non-mucin ligands on other tumor cell types." (PMID 35453656, 2022). "Next, we analyzed whether the BZM-mediated reduction of E-selectin, ICAM-1, and VCAM-1 has a functional consequence for the adhesion of human tumor cells to HUVECs in laminar flow adhesion assays." (PMID 35031433, 2022). "STAT3 silencing also could reduce the expressions of cytokines IL-6, IL-1β and inflammatory mediators ICAM1 and COX2 in the tumor microenvironment." (PMID 35513871, 2022). "Increased tumor infiltration and mesenchymal shift were observed in irradiated mice; however, this was not the case in tumors formed by U87MGsh‐ICAM‐1." (PMID 34813169, 2022). "To further determine whether ATO regulates IL-1β secretion by modulating macrophage function, we measured ICAM1 levels in HNSCC cells after combinatorial treatment with ATO and CM or the addition of ATO to the THP-1–tumor cell coculture system." (PMID 36264639, 2022). "Inhibition of TGF-β enhanced the proinflammatory potential of TANs (N1), including cytotoxic CD8+ T lymphocyte activation, reactive oxygen species-dependent direct killing of tumor cells, and high expression of proinflammatory cytokines such as TNF-α and CCL3 and the costimulatory molecule ICAM-1." (PMID 35328639, 2022). "Moreover, the low expression of adhesion molecules including ICAM-1 and 2, VCAM-1 and CD34 in tumor endothelial cells (EC) inhibit the effector T-cell from adhering to the EC and being transported to the tumor." (PMID 35401561, 2022). "The increased expression of ICAM1 and ITGB2, which mediate cell adhesion, may lead to enhanced tumor aggressiveness." (PMID 36159780, 2022).
tumor (continued). "In response to EGFR CAR-T cell activation and IFN-γ secretion, the tumor cells upregulated the expression of the intercellular adhesion molecule-1 (ICAM-1), which in turn enabled the progressive entry of EGFR CAR-T cells from the periphery to the center of tumor islets." (PMID 35466279, 2022). "Therefore, we suggest that ICAM-1 neutralizing antibody serves as a novel therapeutic target because it induces the inactivation of SRC and suppresses tumor malignancy." (PMID 35487888, 2022). "Simvastatin could decrease CCL3 expression from cancer cells and ICAM-1, VCAM1, IL-6, and CCL2 expression from CaMSCs, disrupting the crosstalk of the cancer cells and tumor microenvironments (TME) and inhibiting tumor progression." (PMID 36430409, 2022). "In addition, the ICAM-1/LFA-1 pathway regulates important cell–cell interactions including leukocyte adhesion and migration, especially the killing of tumor cells by natural killer cells and cytotoxic T lymphocytes (CTLs)." (PMID 36016615, 2022). "As tumour cells do not express αLβ2 integrins, they use leukocytes as linker cells to adhere to the vascular endothelium by means of an ICAM-1/LFA-1 interaction." (PMID 34693476, 2022). "Except for fibroblasts, a total of 937 endothelial cells were also obtained, which were subclustered into five subsets, including extra-alveolar capillary ECs (Endo-C1; EDN1+), tumor ECs (Endo-C3; INSR+), and other ECs (Endo-C2, ICAM1+; Endo-C4, MAP1B+; Endo-C5, CXCR4+)." (PMID 36046337, 2022). "Finally, by treating the cells with a neutralizing antibody capable of inhibiting ICAM-1, we found decreased SRC activity, tumor metastasis, and angiogenesis." (PMID 35487888, 2022). "CRT also increases expression of intercellular adhesion molecule (ICAM)-1 and vascular cell adhesion molecule (VCAM)-1 on tumour endothelial cells via nuclear factor kappa-light-chain-enhancer of activated B cells (NF-κB) activity, thereby improving anti-tumour immune responses." (PMID 36497148, 2022). "Immunosuppressive factors, such as VEGF, downregulate the expression of ICAM-1 on the tumor endothelium, contributing to the lack of adhesiveness/localization of T cells." (PMID 35552271, 2022). "Adhesional factors on the BBB endothelium such as ICAM-1, VCAM-1, or ACKR1 may be upregulated by IL-1β or IFN-γ, which can be delivered via convection-enhanced delivery (CED) directly to the tumor site." (PMID 34771532, 2021). "Once the tumor is established, ECs not only form the blood vessels that supply oxygen and nutrients to tumoral cells, but also communicate with them via angiocrine factors such as HGF and ICAM-1, which promote tumor progression." (PMID 35008212, 2021). "Some s find out about exhibit that ICAM1 (intercellular adhesion molecule-1)-specific CAR-T cells have been in a position to efficiently recognize ICAM1 expressing TNBC cells, and they can effectively minimize the growth of TNBC tumor inside and outside." (PMID 35111680, 2021). "Unsurprisingly, the cytokine array data revealed a significant increase in secreted ICAM-1 by MDA-MB-231 cells, which suggests that hydrolysis products may promote development of a more aggressive tumor phenotype." (PMID 34404457, 2021). "We showed that the expression of proteins specific to ECs (ACE+, VWF+), their differentiation (CD31+, CD 133+, CD105+, CD34-), their adhesion properties (ICAM-1+, VCAM-1+, CD62-L+), and their barrier formation (ZO-1+) were all downregulated in tumor-derived ECs." (PMID 34445568, 2021). "Prospectively, a combination of inflammatory factors (such as TNF-α) and adhesion molecules (such as ICAM1 and ALCAM) neutralizing antibodies might be a useful adjuvant therapy to prevent tumor metastasis in the process of tumor treatment." (PMID 34222020, 2021).
tumor (continued). "In kidney and pancreatic tissues, the forced overexpression of LTα promotes lymphoid aggregate formation (containing T cells, B cells, and APCs) and tumor vascular reprograming, as indicated by increased expression of VCAM-1, ICAM-1, MAdCAM, and PNAd on VEC/HEV." (PMID 34054879, 2021). "Lentiviral cDNA mediated up-regulation of ICAM1 from 1% to 14% of cells in TN1 PDX models dramatically promoted spontaneous metastasis to the lungs, even upon normalization to the slightly increased tumor weight." (PMID 34381029, 2021). "Finally, blocking ICAM1 interactions significantly inhibits CTC cluster formation, tumor cell transendothelial migration, and lung metastasis." (PMID 34381029, 2021). "The specific markers that we analyzed include tumor stem cell markers (CD24, CD44), markers of immunosuppression (CD47, PD-L1), markers of cell adhesion (CD49d, ICAM-1), markers of lymphocytes co-stimulation (CD80, CD86), and markers of antigen presentation (MHC class I, MHC class II)." (PMID 34411144, 2021). "Hsa_circ_0007456 can also interact with miRNAs and endogenously adsorb miR-6852-3p, blocking its binding to the downstream target gene intercellular adhesion molecule 1 (ICAM-1) 3’-UTR, affecting the expression of ICAM-1 and promoting the immune escape of tumor cells." (PMID 34540684, 2021). "Moreover, we separated TAECs from tumor tissues of insufficient RFA‐treated mice and sham operation‐treated mice, and found that ICAM‐1 expressions in TAECs from insufficient RFA‐treated mice were increased compared with those from sham operation‐treated mice." (PMID 33643788, 2021). "The anti-tumor “N1” phenotype exhibited increased tumor cytotoxicity, elevated expression of CXCL13, CCL3, CCL6, CXCL10, TNFα and ICAM-1 and low ARG1 content, while the pro-tumor “N2” neutrophils expressed high levels of ARG1, MMP9, VEGF and several cytokines, including CCL2, CCL5, CCL17 and CXCL4." (PMID 34572138, 2021). "Interaction of endothelial VCAM-1 with tumor cell VLA-4 and/or endothelial ICAM-1 with platelet αIIbß3 triggers an “outside-in” signaling cascade in endothelial cells that induces the digestion of tight junctions, cytoskeletal rearrangement, and endothelial retraction." (PMID 33042789, 2020). "For example, Smad7 retains the NF-κB inhibitor alpha (IκBα) expression; inhibits NF-κB-activated genes such as tumour necrosis factor alpha (TNFα), interleukin 1 beta (IL1β), and intercellular adhesion molecule 1 (ICAM1); and thereafter plays an anti-inflammatory role in several tumour cell lines." (PMID 33282009, 2020). "To evaluate the level change of cytokine in tumor microenvironment after TGF-β blocking, we examined the metastasis chemoattractants secreted by primed neutrophils in the microenvironment, including MMP-9, IL-6, ICAM-1, and NE." (PMID 32201528, 2020). "Additionally, we stained for E-selectin, ICAM-1, and VCAM-1 on tumor endothelial cells roughly 24 hours post FUS+MBs BTB/BBB opening in intracranial B16F1cOVA and in the less immunogenic B16F1 tumors." (PMID 32754281, 2020). "Interestingly, an experimental study showed a significant increase in CD8+ T cell infiltration and tumor rejection following extensive Treg depletion, a finding that might be associated to tumor vasculature normalization, which express increased levels of VCAM‐1 and ICAM‐1 on endothelial cells." (PMID 32620049, 2020). "Our results showed that ICAM1-specific CAR-T cells had no inhibitory effect in tumor growth when compared with the PBS control group." (PMID 33072116, 2020). "Tumor lysis might exert functionally via the LFA-1/ICAM-1 pathway or NKG2D receptor and MHC-related ligands (MIC A/B) and the ULBP family on tumor cells, which results in up-regulated secretion of perforin and granzyme." (PMID 32349280, 2020). "In the histological analyses of the tumor, we found prominent infiltrate of human T cells in the ICAM1-CAR-T group but not in the control CAR-T or PBS group." (PMID 33072116, 2020).
tumor (continued). "For example, coxsackievirus A21 (CVA21) has a natural tropism for tumor cells, recognizing highly expressed receptors and intercellular adhesion-1 molecules (ICAM-1/CD54) on the surface of tumor cells for subsequent penetration, replication, and their elimination." (PMID 33348704, 2020). "Therefore, to examine the impact of vesicles isolated from grapefruit on tumour cell aggressiveness, we evaluated the expression of cysteine protease cathepsins and intercellular adhesion molecule 1 (ICAM), two important markers of the tumour spreading." (PMID 33371199, 2020). "In addition, IHC staining revealed that TGF-β1, BMP4, ICAM1, and VCAM1 expression was decreased in the ARNTL2-knockdown xenograft tumor tissues." (PMID 32826856, 2020). "Some studies have found that radiation induces upregulation of MHCI, intercellular adhesion molecule 1 (ICAM-1), NKG2D ligand (NKG2DL), death receptor Fas, and costimulatory molecule CD80 on tumor cells, which enhances both antigen presentation and T cell recognition." (PMID 32000802, 2020). "Tumor volume, lung metastasis, and tumorigenic molecules (VEGF-A, HIF-1α, MMP-9, ICAM-1, VCAM-1, and phospho-NF-κB and phospho-STAT-3) were significantly induced in mice injected with ESM-1-overexpressing 4T1 cells and greatly enhanced in those injected with ESM-1-overexpressing RT-R-4T1 cells." (PMID 32466580, 2020). "Costimulatory molecules (CD80), intercellular adhesion molecule 1 (ICAM-1), stress ligands (NKG2DL), and death receptor Fas on the tumor surface are also upregulated after radiation, which makes the tumor cells more sensitive to the recognition and killing of cytotoxic T lymphocyte." (PMID 32992835, 2020). "We have proved that ICAM1-specific CAR-T cells were not able to kill SKBR3 cells in vitro and in vivo, indicating that ICAM1 would be an ideal tumor-associated antigen target for CAR-T cells to treat TNBC." (PMID 33072116, 2020). "ICAM1 (Intercellular adhesion molecule 1; CD54), a member of immunoglobulin super family (Igsf), is necessary for cell adhesion and acts as an important player in inflammation-induced tissue adhesion, tumor metastasis and immune response." (PMID 33099324, 2020). "Consistent with the in vitro results, mice injected with ESM-1-overexpressing 4T1 cells exhibited significant increases in tumor volume, lung metastasis, metastasis-related molecules (VEGF, MMP-9, ICAM-1, and VCAM-1), and transcription factors (HIF-1α, phospho-NF-κB, and phospho-STAT-3)." (PMID 32466580, 2020). "The expression of intercellular adhesion molecule 1 (ICAM-1) was reduced in E10 and G11 cells, which may also be a stimulating factor for tumor metastasis." (PMID 32983976, 2020). "In our model VEGF production is partially ICAM-1 dependent, which may explain why LSEC ICAM-1/tumor LFA-1 crosstalk modulates LSEC migration in vitro and LSEC angiogenic response inside the tumor foci." (PMID 31511625, 2019). "Together, these results suggest that despite having high ICAM-1 expression, EWS-FLI1 ‘low’ cells are able to evade T-cell mediated apoptosis by simultaneously upregulating factors that negatively impact the T-cell anti-tumor response, such as PD-L1 and PD-L2." (PMID 31164960, 2019). "Interestingly, Trapoxin A treatment led to the up-regulation of costimulatory and adhesion molecules (CD80, CD86, HLA-DR, HLA-ABC, and ICAM-1) in AML cells, inducing tumor immunity." (PMID 31739588, 2019). "However, it has been shown that anti-angiogenic drugs normalize the tumor vasculature and induce the upregulation of the leukocyte adhesion molecules ICAM-1 and VCAM-1 on tumor endothelial cells, leading to increased T cell infiltration." (PMID 30800125, 2019). "By contrast, CAR-T cells with micromolar affinity only attack tumor cells with high levels of ICAM-1 but not healthy cells with low levels of ICAM-1, leading to less toxicity." (PMID 31640814, 2019).
tumor (continued). "Similar to the effect seen with T-cell co-culture, tumor cell treatment with IFN-γ leads to an increase in ICAM-1 expression in the absence of changes in EWS-FLI1 mRNA expression." (PMID 31164960, 2019). "In this study, we determined 11 immunomodulators that are involved in tumor escape mechanisms and found 9 immunomodulators (LAG-3, TIM-3, CTLA-4, IFN-γ, ICOS, ICAM-1, TIGIT, NKG2A, and VISTA) that were upregulated in both high-immune score group and high-stromal score group." (PMID 31781309, 2019). "Further, when injected into nude mice, a significant reduction was observed in subcutaneous tumor growth and ability to metastases liver with ICAM-1+ LM-H3 cells compared to ICAM-1 negative cells." (PMID 31231358, 2019). "As many studies report the association between tumor relapse or drug resistance and ICAM-1 overexpression, ICAM-1 targeting has obvious advantages even if ICAM-1 is not uniformly elevated in early stage cancers." (PMID 31337787, 2019). "Tumor cells do not express such integrins; nevertheless, they possess the ability to express ICAM-1 and use leukocytes as linker cells to adhere to the vascular endothelium." (PMID 30657059, 2019). "Furthermore, TECs have been described as being “activated” and “chronically inflamed”; they express adhesion molecules ICAM-1, VCAM-1, and E-selectin, through which they interact with proinflammatory and tumor cells." (PMID 31600937, 2019). "As CVA21 is dependent on human ICAM-1 for cell entry, only human model systems or immunocompromised human xenograft murine models allow in vivo testing of CVA21, with the latter preventing exploration of the role of adaptive anti-tumor immunity." (PMID 31262361, 2019). "Next, we aimed to clarify whether the expression level of MAN1A1 in tumours could impact the prognostic value of ALCAM and ICAM-1." (PMID 31659304, 2019). "Upon further examination of the cellular mechanisms responsible for CVA21-induced anti-tumor immunity we have identified the importance of type I IFN for NK cell activation, and demonstrated that both ICAM-1 and plasmacytoid dendritic cells were key mediators of this response." (PMID 31262361, 2019). "In addition, proteins involved in tumor cells invasion such as CXCL1, CXCL5, and MMP1 were displayed to be expressed and interacted with ICAM-1 and TGFβ2 in the network analysis." (PMID 29966014, 2018). "The ICAM1 expression in these samples correlated to the individual mRNA expression in tumor and normal samples with the exception of one patient sample with HER2 enriched tumor." (PMID 30082828, 2018). "Interestingly, upon ICAM-1 blockade, the expression of the chemotactic receptor CCR7 augments in tumor infiltrating lymphocytes and in in-vitro de-clustered T cells, as well as their ability to transmigrate across lymphatic endothelial cells." (PMID 30258446, 2018). "Mutant ICAM1 vaccination did not protect mice from challenge with the unrelated MOC2 tumor cell line." (PMID 29423108, 2018). "In addition, the downregulation of adhesion molecules, such as vascular cell adhesion molecule 1 (VCAM1) and intercellular adhesion molecule 1 (ICAM1), leads to an enhancement of a tumor vasculature barrier that inhibits T cell arrest and transmigration." (PMID 30115069, 2018). "N1 TANs were cytotoxic to tumour cells via an oxygen radical-dependent mechanism and had increased tumour necrosis factor alpha (TNF-α) and intercellular adhesion molecule 1 (ICAM-1) expression, whereas N2 TAN expressed high levels of arginase which is known to suppress T cell immunity." (PMID 30137312, 2018). "In summary, we propose that LFA-1/ICAM-1 mechanism is not needed for T-lymphocyte transendothelial transit neither for their advancement through the tumor stroma." (PMID 30258446, 2018). "Interestingly, synergy between ICI and extracranial tumor enhances CD8+ T cell recruitment to the brain by peripheral expansion of effector T cells and upregulation of ICAM-1 and VCAM-1 receptors on blood vessels within the tumor." (PMID 30301252, 2018).